CDKAL1 (CDKAL1 threonylcarbamoyladenosine tRNA methylthiotransferase)
Diseases named in the same sentence as CDKAL1 in open-access papers (continued):
Sharing a sentence is not in itself a finding about the gene and the disease.
gastric cancer (4 papers, 2023 to 2025). A primary or metastatic malignant neoplasm involving the stomach. "Studies have shown that FTO is overexpressed in gastric cancer and that its demethylase activity upregulates CDKAL1, which promotes cell proliferation and mitochondrial fusion, thereby increasing the resistance of gastric cancer to chemotherapy with 5-Fu." (PMID 41584846, 2025).
breast carcinoma (3 papers, 2021 to 2023). "A locus, rs9368197, located within CDKAL1 (intron) was detected to be associated with increased breast cancer risk in European American women." (PMID 35568861, 2022). "rs9368197 in an intron of CDKAL1 is associated with breast cancer risk." (PMID 33892787, 2021).
Hyperglycemia (3 papers, 2013 to 2023). An increased concentration of glucose in the blood. "Previous reports showed that high fat diet intake and β-cell-specific Cdkal1 knockout mice induced β-cell hypertrophy and increased β-cell/islet area and β-cell mass content in the pancreas due to chronic hyperglycemia state." (PMID 27056903, 2016). "We found that Cdkal1 expression in pancreatic islets was decreased following incubation in high glucose, which could contribute to β-cell dysfunction in settings of hyperglycemia." (PMID 23442068, 2013).
bladder cancer (2 papers, 2008 to 2022). "CDKAL1 gene maps at 6p22 where a highly prevalent amplification in bladder cancer compared to other cancer types has been registered." (PMID 35841413, 2022). "In two recent studies knock down experiments of E2F3 in bladder cancer cells lines with 6p amplification was shown to strongly reduce cellular proliferation whereas a similar knock down of CDKAL1 did not have this effect." (PMID 18237450, 2008).
Glucose intolerance (2 papers, 2013 to 2015). Glucose intolerance (GI) can be defined as dysglycemia that comprises both prediabetes and diabetes. "Cdkal1-deficient β-cells have impaired glucose-induced insulin secretion, and Cdkal1 knockout mice develop glucose intolerance due to aberrant insulin synthesis." (PMID 24204302, 2013). "Indeed CDKAL1 risk allele carriers display an insulin secretory defect that is concomitant with higher levels of proinsulin, and beta cell-specific deletion of Cdkal1 in mice results in glucose intolerance due to reduced insulin secretion and impaired proinsulin conversion." (PMID 25634229, 2015).
Hypertension (2 papers, 2021 to 2024). The presence of chronic increased pressure in the systemic arterial system. "Moreover, CDKAL1 rs9295474 was notably associated with hypertension SBP and DBP in individuals of European ancestry." (PMID 38674857, 2024).
rhabdomyosarcoma (2 papers, 2023 to 2024). A rare aggressive malignant mesenchymal neoplasm arising from skeletal muscle. "CDKAL1 expression is upregulated in patients with worse prognoses and is essential for maintaining CSCs in rhabdomyosarcoma (RMS) and common cancers." (PMID 36786012, 2023).
bipolar disorder (1 paper, 2022). A disorder of the brain that causes unusual shifts in mood, energy, activity levels and the ability to carry out day-to-day tasks. "The top one gene CDKAL1 encoding a member of the methylthiotransferase family, a subfamily of the radical S-adenosylmethionine (SAM) superfamily, has been reported be involved in the susceptibility to T2DM in Europeans and Japanese and to bipolar disorder in Europeans." (PMID 36329495, 2022).
endometrial cancer (1 paper, 2023). Primary or metastatic malignant neoplasm involving the endometrium (mucous membrane that lines the endometrial cavity). "When examining the linear parental genes, CDKAL1 is known to be implicated in endometrial cancer tumorigenesis." (PMID 37213253, 2023).
glioblastoma (1 paper, 2023). The most malignant astrocytic tumor (WHO grade IV). "Surprisingly, CDKAL1 knockdown markedly attenuated the coprecipitation of eIF4A and eIF4G by m7GTP beads, and this was also confirmed in the glioblastoma initiating cells MGG8, and MGG18." (PMID 36786012, 2023).
insulinoma (1 paper, 2022). "Diminished Fe/S cluster biosynthesis was shown to mitigate the function of Cdkal1, an Fe/S cluster enzyme crucial for proinsulin processing in iron-regulatory protein 2-deficient mice and rat insulinoma cells." (PMID 35453472, 2022).
iron deficiency (1 paper, 2022). "CDKAL1 belongs to the methyltransferase family, whose function is impaired by cellular iron deficiency." (PMID 36361777, 2022).
macrosomia (1 paper, 2025). "After adjusting for confounding factors such as maternal age and BMI, we found that the maternal CDKAL1 gene variants were significantly associated with APO, particularly the risks of low birth weight and macrosomia." (PMID 40133860, 2025). "After adjusting for GDM alongside the traditional risk factors, the CDKAL1 genetic marker remained significantly associated with low birth weight and macrosomia, with the ORs showing no significant alterations." (PMID 40133860, 2025). "The CDKAL1 genetic marker was associated with the risk of adverse pregnancy outcome (OR: 2.51, 95%CI: 1.47, 4.28), low birth weight (OR: 19.80, 95%CI: 2.15, 182) and macrosomia (OR: 2.40, 95%CI: 1.17, 4.93), but not with preterm birth (P = 0.105) after adjusting for traditional risk factors." (PMID 40133860, 2025). "Our study revealed that the maternal CDKAL1 gene variants was associated with the risk of APO and its components, including low birth weight and macrosomia, but not with preterm birth." (PMID 40133860, 2025).
ovarian carcinoma (1 paper, 2024). A malignant neoplasm originating from the surface ovarian epithelium. "Through biological information screening, RT-qPCR and WB verification, it was found that VPS13B, TBC1D22A, PPP3CA, CUX1 and PPP1R15A were highly expressed in cisplatin-resistant tissues of ovarian cancer, while PLGRKT, CDKAL1 and TAP1 were low expressed." (PMID 39103807, 2024). "VPS13B, TBC1D22A, PPP3CA, CUX1 and PPP1R15A were identified as poor prognostic genes for cisplatin resistance in ovarian cancer, while PLGRKT, CDKAL1 and TAP1 were identified as good prognostic genes." (PMID 39103807, 2024). "VPS13B, TBC1D22A, PPP3CA, CUX1 and PPP1R15A were identified as poor prognostic genes of cisplatin resistance in ovarian cancer, while PLGRKT, CDKAL1 and TAP1 were identified as good prognostic genes." (PMID 39103807, 2024).
cancer (6 papers, 2017 to 2024). A tumor composed of atypical neoplastic, often pleomorphic cells that invade other tissues. "Furthermore, CDKAL1 expression levels in these cancers were associated with a worse prognosis." (PMID 36786012, 2023). "We examined the mutations of both CDKAL1 and CENPT in different BC cell lines using the Cancer Cell Line Encyclopedia (CCLE) online database." (PMID 38217005, 2024). "CDKAL1 acts as a tRNA-modified methylthiotransferase, facilitating the production of cytokines that are characteristic of cancer stem cells." (PMID 39103807, 2024). "We further validated that CDKAL1 deficiency resulted in the loss of the undifferentiated state, as shown by the loss of canonical CSC‐markers in each cancer type in vitro." (PMID 36786012, 2023). "It is reported that a tRNA‐modifying methylthiotransferase CDKAL1 promotes cancer stem‐like cells (CSC)‐factor SALL2 synthesis by assembling the eIF4F translation initiation complex." (PMID 36786012, 2023). "To test whether CDKAL1 impacts clinical outcomes in other cancers, we analyzed public gene expression datasets obtained from The Cancer Genome Atlas (TCGA)." (PMID 36786012, 2023). "To examine whether CDKAL1 was crucial for maintaining CSC properties of these cancers, we prepared two or three cell lines per type." (PMID 36786012, 2023). "Thus far, we showed that CDKAL1 promoted CSC‐related traits maintenance in various cancers." (PMID 36786012, 2023). "We next asked whether the mechanism of CSC maintenance by CDKAL1 is limited to cancer cells." (PMID 36786012, 2023). "Here, we unveiled the pivotal role of CDKAL1 in cancer biology, which was independent of the canonical role of CDKAL1 as an RNA‐modifying methyltransferase." (PMID 36786012, 2023). "CDKAL1 is required to maintain the CSC‐related traits in RMS, as well as common cancers." (PMID 36786012, 2023).
metabolic disease (4 papers, 2015 to 2017). A congenital disorder (due to inherited enzyme abnormality) or acquired (due to failure of a metabolically important organ) disorder resulting from an abnormal metabolic process. "Therefore, we speculate that the potential molecular mechanism of ECD is to promote the CDKAL1 expression, ameliorate islet cell function, and raise insulin levels to regulate the metabolic disorder." (PMID 26504476, 2015).
tumor (2 papers, 2017 to 2023). "We also confirmed that the CDKAL1 deficit induced differentiation, as shown by the loss of CD133 and the gain of myosin heavy chain (MyHC) both in vitro and in vivo, and attenuated the tumor‐propagating potential of RMS‐YM cells in immunocompromised mice." (PMID 36786012, 2023). "After transformation, the expression levels of Cdkal1 were elevated, and HRas/shp53‐C2C12 cells acquired anchorage‐independent growth potential, resistance to differentiation cues, and tumor‐propagating potential." (PMID 36786012, 2023). "The forces driving Sc/NE‐like and GU tumours into one consensus cluster are most likely a high proliferation rate and frequent E2F3, CDKAL1 and SOX4 genomic amplification at 6p22, which are characteristic of both subtypes." (PMID 28195647, 2017).
psychiatric disease (1 paper, 2021). "We included one positive control SNP, shown to alter neural tissue gene expression, and one control locus near CDKAL1 not a priori associated with psychiatric disease." (PMID 34294677, 2021).
retinopathy (1 paper, 2017). "And functional study which investigates the role of CDKAL1 in the pathophysiological process of retinopathy has not been reported yet." (PMID 28821857, 2017).
CDKAL1 also shares sentences with these, for which no sentence is quoted: glioma (2 papers); kidney (2); liver cancer (2); prediabetes (2); stomach cancer (2); ulcerative colitis (2); Abdominal obesity (1); abnormal glucose tolerance (1); acne (1); cardiovascular disease (1); chronic kidney disease (1); colon cancer (1); coronary artery disease (1); deficient (1); diabetes insipidus (1); diabetic retinopathy (1); endometriosis (1); fatty liver (1); genetic disorder (1); hyperlipidemia (1); hypertriglyceridemia (1); inflammatory bowel disease (1); invasive breast carcinoma (1); kidney transplant (1); lipodystrophy (1); maturity onset diabetes of the young (1); metabolic syndrome (1); microcephaly (1); optic atrophy (1); Parkinson disease (1).
A further 12 diseases each share a sentence with CDKAL1 in 1 paper.